TBXT (T-box transcription factor T)
Diseases named in the same sentence as TBXT in open-access papers (continued):
Sharing a sentence is not in itself a finding about the gene and the disease.
chordoma (continued). "The dysregulation of TBXT regulated by SEs is the main feature of the regulatory environment in chordoma cells." (PMID 32714929, 2020). "Increased VEPH1 expression is driven by Brachyury/TBXT, a T-box transcription factor highly expressed in chordoma, a rare cancer derived from notochord remnants." (PMID 31500637, 2019). "In particular, the striking consistency of TBXT expression in chordoma has gathered increasing attention as a tumor-defining and possibly causative characteristic, pointing at the re-activation or maintenance of the embryonic notochord program as the cause." (PMID 31221659, 2019). "Next, we asked whether the T-DARPins effectively and specifically bind endogenous TBXT in chordoma cells." (PMID 40901948, 2025). "A potential therapeutic target is the TBXT gene (also known as brachyury), which is amplified in 7%, duplicated in 27%, and overexpressed in more than 90% of cases and has been identified as the key driver of chordoma development and progression." (PMID 40901948, 2025). "Besides the main impact of TBXT on the cell cycle and identity of chordoma cells, analysis of the core TBXT regulome identified additional gene programs." (PMID 40901948, 2025). "Finally, we aimed to provide direct evidence that T-DARPins inhibit the interaction of TBXT with its genomic binding sites in chordoma cells." (PMID 40901948, 2025). "In summary, the TBXT regulome contains multiple pharmacologically tractable proteins, including some targets of clinically approved drugs, and therefore represents a valuable resource for future chordoma drug discovery campaigns." (PMID 40901948, 2025). "In summary, IGFBP3 may act as a regulator that fine-tunes specific transcriptional effects of TBXT in chordoma cells to create optimal growth conditions." (PMID 40901948, 2025). "We then focused on characterizing T-DARPins A2, B1, and D4, as they showed the strongest binding to TBXT, displaced TBXT from DNA in chordoma cells within 24 hours, and may act via different modes as seen from the EMSA (D4 versus A2 and B1)." (PMID 40901948, 2025). "TBXT plays a crucial role in regulating chordoma cell function." (PMID 40901948, 2025). "It is, therefore, tempting to speculate that TBXT-mediated MTAP suppression may phenocopy this effect in chordoma." (PMID 40901948, 2025). "However, after the surgery, histopathology revealed the presence of brachyury protein (T-box transcription factor T), which is characteristic of a chordoma." (PMID 38721258, 2024). "For example, chordoma cells express brachyury (T), a notochordal T-box transcription factor (TBXT)." (PMID 38652222, 2024). "It expressed the embryonic transcription factor brachyury/TBXT (seen in Western blots), which is critical in vertebrate mesoderm and notochord development and is considered a reliable marker of most chordomas." (PMID 39684443, 2024). "Apart from these mutations, TBXT/TBXT.2 genes also induce EMT in humans when over expressed in carcinoma cells, and it has also been recorded that duplications of the Brachyury gene cause vertebral column chordomas." (PMID 39191278, 2024). "Genes marked on the volcano plot were either implicated earlier in chordoma biology (e.g. keratins—KRT8, KRT18, KRT19, TBXT, LMX1A, and EGFR) or identified by outstanding p-value (e.g. IL11, CD24), high absolute fold-change (e.g. GABRA1) or DMR result (e.g. MNX1)." (PMID 37434245, 2023). "Moreover, the silencing of TBXT in chordoma cell line U‐CH1 resulted in decreased cell proliferation." (PMID 34837714, 2022). "Patients with higher TBXT expression have significantly shorter progression-free survival than those with lower expression, and TBXT inhibits Paclitaxel-induced apoptosis in primary chordoma cell lines via carbonic anhydrase IX." (PMID 36520826, 2022).
chordoma (continued). "As TBXT is becoming an attractive target for molecular targeted therapy in chordoma, a simple and reliable T‐ARMS‐PCR offers an effective screening method for rs2305089 in these patients and might pave the way for new molecular targeted therapy techniques." (PMID 34837714, 2022). "Germline duplication of TBXT was also observed in the familial type of chordoma." (PMID 34837714, 2022). "Bibliometric analysis showed that chemotherapy, PTEN, EGFR, and TBXT were related to chordoma." (PMID 36520826, 2022). "Thus, shRNA- and sgRNA-mediated TBXT repression in chordoma cell lines have been shown to suppress cell growth and induce apoptosis." (PMID 34330313, 2021). "Besides TBXT and RTKs, several other signaling factors have been found to be activated or misexpressed in chordoma." (PMID 31221659, 2019). "TBXT acts on a network of over 600 genes in chordomas encompassing cell cycle regulators, producers of extracellular matrix, and growth factors, making it likely that these play a role in the pathogenesis of chordomas, but the functional impact of the rs2305089 SNP has yet to be elucidated." (PMID 40323130, 2025). "To substantiate this association, we mapped the levels of ISGs across the RNA-seq and proteomics experiments and observed down-regulation of ISGs upon TBXT inhibition in all datasets, suggesting that chordoma cells might have high baseline interferon signaling driven by TBXT." (PMID 40901948, 2025). "Finally, the T-DARPins themselves could be developed into clinical drugs for chordoma or other TBXT-expressing cancers if delivery to cells in vivo can be achieved." (PMID 40901948, 2025). "However, additional studies with multiple chordoma cell lines or primary chordoma organoids are needed to investigate all possible fates of chordoma cells after TBXT inhibition and to develop biomarkers of differentiation for guiding future TBXT-targeted therapies." (PMID 40901948, 2025). "Furthermore, we conducted immunofluorescence staining of FN1 and the chordoma marker TBXT." (PMID 37784253, 2023). "While TBXT had been the only statistically significant dependency gene identified, we hypothesized that this could be attributed to the small set of chordoma cell lines screened, and that the full range of tumor dependencies in chordoma remained to be discovered." (PMID 37024492, 2023). "Moreover, due to the low TBXT expression in most normal adult tissues, exclusive cancer‐specific expression, and its roles in epithelial–mesenchymal transition, TBXT has been considered as a therapeutic target for chordoma." (PMID 34837714, 2022). "Further, chordoma growth in cell models could be inhibited by TBXT silencing." (PMID 34070849, 2021). "In particular, sustained expression of TBXT – encoding the notochord regulator protein brachyury – is hypothesized as a key driver of chordoma, yet experimental evidence is absent." (PMID 31221659, 2019). "Upon mesoderm induction, TBXT expression rose rapidly, peaked at 24 h, and remained comparable to the U‐CH1 chordoma cell line at 48 h." (PMID 40323130, 2025). "In summary, our data indicate that chordoma cells require JAK-STAT signaling driven by TBXT, particularly JAK2, suggesting an immediately applicable strategy for targeted treatment of patients with chordoma using clinically approved JAK2 inhibitors." (PMID 40901948, 2025). "Based on the transcriptomic data of clinical chordoma tissues, RAB3B showed a high correlation with stemness markers, such as TBXT (R = 0.85, p = 5e–15), OCT4 (R = 0.5, p = 0.00016) and NANOG (R = 0.41, p = 0.0027)." (PMID 40135815, 2025). "Consequently, TBXT inhibition could impose a more differentiated identity on chordoma cells." (PMID 40901948, 2025). "The validation of TBXT expression in response to CuB treatment was performed in the representative chordoma cell lines U-CH1, MUG-Chor1, and UM-Chor1 by qRT-PCR, confirming a slight transcriptional downregulation of TBXT." (PMID 40332566, 2025).
chordoma (continued). "Future studies need to determine why chordoma cells exhibit elevated JAK-STAT signaling and to what extent and how TBXT contributes to this characteristic." (PMID 40901948, 2025). "T‐box transcription factor T (TBXT; OMIM: 601397) plays an important role in the pathogenesis and survival of chordoma cells." (PMID 34837714, 2022). "Despite the knowledge that TBXT is the essential chordoma driver, the TBXT-regulated transcriptome is not fully understood." (PMID 40901948, 2025). "The embryonic transcription factor TBXT (brachyury) drives chordoma, a spinal neoplasm without effective drug therapies." (PMID 40901948, 2025). "The EGFR inhibitor afatinib, which we included as a positive control because it down-regulates TBXT, was equally harmful to chordoma cells but, as expected, not to the TBXT-negative and EGFR-inactive U2OS cells." (PMID 40901948, 2025). "In addition to the well‐known chordoma biomarkers (LGALS3 and TBXT), the heatmap also revealed IGKV2, IL13RA2, RAB3B, and MAPK3 highly expressed in chordoma." (PMID 40135815, 2025). "Previous observations in chordomas suggested a role of histone rather than DNA methylation in epigenetic regulation of TBXT." (PMID 37434245, 2023). "The cg01392518 probe upstream of TBXT promoter had also virtually no methylation in chordomas from validation set." (PMID 37434245, 2023). "Afatinib has been verified as a potential treatment for chordomas by targeting EGFR and TBXT." (PMID 36520826, 2022). "TBXT, S100A10, and S100A1 were the pathological markers of chordoma." (PMID 36127333, 2022). "The researchers also indicated a higher mRNA expression of TBXT in patients with AA genotype than in GA sporadic chordoma patients without TBXT gene duplication." (PMID 34837714, 2022). "Together, we showed that part of the TBXT regulome is modulated by IGFBP3, particularly factors involved in the interferon response, suggesting that IGFBP3 can fine-tune the action of TBXT to precisely fulfill the requirements of chordoma cells for survival and proliferation." (PMID 40901948, 2025). "Additionally, several studies have shown that TBXT is consistently expressed in chordomas, regardless of their anatomical location." (PMID 39051200, 2024). "In contrast, the other nine pediatric chordoma patients (diagnosed ≤ 20 years) appeared to have quiet genomes, characterized by low mutational burden and the absence of driver events (alterations in PBRM1, CDKN2A/B, TBXT genes), compared with adult chordoma patients." (PMID 33536423, 2021). "However, our data also support a more direct regulatory relationship: TBXT may act as an upstream transcriptional regulator of IGFBP3 by binding to regulatory elements, potentially explaining its outlier expression in response to T-DARPin expression in chordoma cells." (PMID 40901948, 2025). "Additionally, two genes scoring in our screens (TBXT, SOX9) can be classified as lineage-survival dependency genes: these transcription factors mediate normal development of the embryonic notochord, the cell type from which chordoma is hypothesized to originate." (PMID 37024492, 2023). "To evaluate the roles of other RAB3 members in the chordoma stemness and tumorigenic functions, we found that RAB3A, RAB3C, and RAB3D regulated the proliferation of CH22 cells, whereas they did not control the expressions of stemness markers, such as TBXT, NANOG, OCT4 and SOX2." (PMID 40135815, 2025).
melanoma (16 papers, 2013 to 2025). A malignant, usually aggressive tumor composed of atypical, neoplastic melanocytes. "Other than TBXT, all identified TFs showed appreciable expression (median normalised RSEM > 1) across the SKCM-US melanoma cohort." (PMID 39367275, 2024).
breast cancer (15 papers, 2012 to 2025). A primary or metastatic malignant neoplasm involving the breast. "TBXT promotes bone metastasis in breast cancer by transcriptionally activating oncogene SRY-Box transcription factor 5 (SOX5)." (PMID 38965548, 2024). "TBXT expression resulted in poor prognosis in breast cancer patients treated with tamoxifen." (PMID 38965548, 2024).
lung carcinoma (7 papers, 2019 to 2025). "This approach will refine the understanding of the TBXT regulatory network and provide a platform to investigate epigenetic modifiers and chromatin regulators that are linked to lung cancer." (PMID 40099944, 2025). "Overexpression of TBXT in human lung cancer cell lines is positively associated with resistance to EGFR kinase inhibitors." (PMID 38965548, 2024). "Although fibroblast growth factor receptor 1 (FGFR1) has been implicated in activating TBXT expression in lung cancer through MAPK signaling, the genomic cis‐regulatory regions that mediate this activation are unknown." (PMID 40099944, 2025). "In this study, we present a TBXT epigenetic regulatory landscape from TBXT‐expressing and non‐expressing lung cancer cell lines." (PMID 40099944, 2025). "Although studied for decades in the context of embryonic development, more recent evidence indicates TBXT also plays an active and central role in lung cancer progression and metastasis." (PMID 40099944, 2025). "TBXT overexpression results in significant downregulation of p21, CCND1 (encoding cyclin D1), and phosphorylated Rb (p-Rb), which increases lung cancer resistance to radiotherapy and chemotherapy." (PMID 38965548, 2024). "However, despite this role in cancer progression, our understanding of how TBXT expression is activated and maintained in lung cancer cells is incomplete, which limits advances in targeted therapies." (PMID 40099944, 2025). "Our findings shed light on active chromatin interactions with TBXT expression in lung cancers, pointing to specific DNA elements and regulatory proteins that may be involved." (PMID 40099944, 2025). "However, whether such epigenetic regulation characterizes TBXT expression in lung cancer is unknown." (PMID 40099944, 2025). "Additionally, higher enrichment of repressive marks (H3K27me3) with H460 lost pCREs in non‐TBXT expressing lung cancer cells (A549) compared to H460 may indicate a role in the suppression of TBXT expression in the TBXT non‐expressing environment." (PMID 40099944, 2025). "As the epigenome is dynamic, biological functional validation will be crucial in elucidating the role of the identified pCREs in TBXT regulation, including their potential involvement in MAPK signaling pathways in lung cancer." (PMID 40099944, 2025). "Of the selected lung cancer-related EMT genes, TBXT was exclusively expressed in Cluster 2 and H460 at both gene and protein (brachyury) levels." (PMID 34654834, 2021). "TBXT itself also drives EMT and cancer progression in lung cancer." (PMID 40099944, 2025). "Circularized chromosome capture combined with sequencing (4C‐seq) was employed to analyze physical chromatin interactions at the TBXT loci in the lung cancer cell line H460, a high TBXT‐expressing cell line, compared to H358 and A549, which do not express TBXT." (PMID 40099944, 2025). "We conducted high‐resolution 4C‐seq to detect chromatin interactions with the TBXT promoter (viewpoint) in lung cancer cells that expressed high levels of TBXT mRNA and protein (H460 cells) and those that did not express detectable levels of TBXT mRNA or protein (A459 and H358 cells)." (PMID 40099944, 2025).
prostate carcinoma (7 papers, 2010 to 2025). A carcinoma that arises from epithelial cells of the prostate gland. "Taken together, these findings, and similar evidence indicating that high levels of TBXT mediate cancer progression in other tumor types including breast and prostate cancer, have made TBXT an attractive therapeutic target." (PMID 40099944, 2025).
glioma (6 papers, 2021 to 2025). A benign or malignant brain and spinal cord tumor that arises from glial cells (astrocytes, oligodendrocytes, ependymal cells). "They further investigated the reduced expression of TBXT in gliomas using RNA-sequencing, which revealed that, within the different anatomical structures of the tumor, TBXT is preferentially expressed in sections with a higher concentration of normal cells." (PMID 35409080, 2022). "In their second study, they demonstrated via gene-editing methods for the overexpression of the factor in glioma cells that TBXT-positive cells exhibit reduced invasive and migratory capability and stem cell features." (PMID 35409080, 2022). "Low expression of TBXT is an independent biomarker of poor prognosis in gliomas." (PMID 38965548, 2024). "Herein, we describe a selection of oncogenic (GLI-1/2/3, E2F1–8, STAT3, and HIF-1/2) and tumor suppressor (NFI-A/B, TBXT, MYT1, and MYT1L) TFs that are deregulated in gliomas and are subsequently associated with tumor development, progression, and migratory potential." (PMID 35409080, 2022). "However, TBXT plays a tumor-suppressive biomarker in gliomas." (PMID 38965548, 2024). "TBXT expression was present in normal brains while absent or at low levels in gliomas and was inversely correlated with tumor grade, and TBXT loss was linked to the mesenchymal subtype of GBM." (PMID 35409080, 2022).
metastatic cancer (2 papers, 2023 to 2025). A carcinoma which has spread from the original site of growth to another anatomic site. "This knowledge paves the way for understanding TBXT expression dynamics at the onset and progression of metastatic cancers." (PMID 40099944, 2025).
sacral agenesis (2 papers, 2024 to 2025). "Notably, mutations leading to neural tube defects and/or sacral agenesis have been detected in the coding and noncoding regions of the TBXT gene." (PMID 38418917, 2024).
anorectal malformation (1 paper, 2022). "A causative role is further substantiated by the relationship between CDX2 and other proteins encoded by genes that were previously linked to caudal abnormalities in humans, for example, TBXT (sacral agenesis and other vertebral segmentation defects) and CDX1 (anorectal malformations)." (PMID 34671974, 2022).
atypical teratoid rhabdoid tumor (1 paper, 2022). Atypical teratoid rhabdoid tumor (ATRT) is a highly malignant central nervous system (CNS) rhabdoid tumor (RT) found almost exclusively in children. "SMARCB1 expression is completely absent in both PDC and atypical teratoid/rhabdoid tumor (AT/RT), and TBXT and cytokeratin immunoexpressions of PDC are diffuse and strong, and combining SMARCB1 with TBXT staining helps to distinguish PDC from AT/RT." (PMID 36520826, 2022).
Cenani-Lenz syndrome (1 paper, 2019). Cenani-Lenz syndrome (CLS) is a congenital malformation syndrome that associates a complex syndactyly of the hands with malformations of the forearm bones and similar manifestations in the lower limbs. "Examples of disorders we were able to confirm through this approach in this study are TBXT-related myelomeningocele,36APC-related Cenani–Lenz syndrome, and XRCC2-related Fanconi anemia." (PMID 30237576, 2019).
Hemivertebrae (1 paper, 2023). Absence of one half of the vertebral body. "Vertebral abnormalities are part of the common terminal 6q deletion phenotype, and TBXT (T-Box Transcription Factor T, MIM*601,397) is suggested to play a role in the aetiology of hemivertebrae." (PMID 36935482, 2023).
sarcoma (1 paper, 2021). A usually aggressive malignant neoplasm of the soft tissue or bone. "Consistent with diagnostic IHC testing, the TBXT gene that encodes the transcription factor brachyury was highly expressed in both samples compared to the TCGA sarcoma and POG570 data sets." (PMID 34931022, 2021).
scoliosis (1 paper, 2025). A congenital or acquired spinal deformity characterized by lateral curvature of the spine. "Recently, an Alu element in TBXT was identified as the mechanism for tail loss in human‐primate ancestors, and a SNP in TBXT was associated with scoliosis in Chinese patients." (PMID 40323130, 2025).